CRYGN (crystallin gamma N)
Tractability: No criterion of Open Targets' tractability assessment is met for any kind of drug.
Gene: Protein-coding gene on chromosome 7 (151,428,832 to 151,440,813, reverse strand). Ensembl gene ENSG00000127377.
Gene Ontology:
Molecular function: structural constituent of eye lens
Biological process: lens development in camera-type eye; visual perception
Genetic constraint (gnomAD): Loss-of-function variants: 17 observed, 15.61 expected, observed/expected ratio (o/e) 1.09, 90% interval 0.74 to 1.62. The upper end of that interval is the gene's LOEUF score, 1.62, which puts it in group 6 of 6, group 1 being the genes least tolerant of losing a copy. Missense variants: 210 observed, 210.75 expected, observed/expected ratio (o/e) 1, 90% interval 0.89 to 1.12. Synonymous variants: 75 observed, 74.23 expected, observed/expected ratio (o/e) 1.01, 90% interval 0.84 to 1.22.
Homologues: Orthologues: chimpanzee CRYGN (98% identical), macaque CRYGN (92% identical), rat Crygn (71% identical), mouse Crygn (70% identical), pig CRYGN (70% identical), rabbit CRYGN (70% identical), guinea pig CRYGN (69% identical), dog CRYGN (67% identical), tropical clawed frog crygn (60% identical), zebrafish crygn1 (57% identical), zebrafish crygn2 (55% identical). Paralogues in human: CRYBA1 (30% identical), CRYBA2 (29% identical), CRYBB3 (29% identical), CRYGC (29% identical), CRYGS (29% identical), CRYBB1 (28% identical), CRYGD (28% identical), CRYGB (27% identical), CRYBA4 (27% identical), CRYGA (25% identical), CRYBG3 (23% identical), CRYBG1 (23% identical), and 2 more.
Diseases named in the same sentence as CRYGN in open-access papers:
CRYGN is named in the same sentence as 7 diseases in open-access papers, as found by Europe PMC text mining. Sharing a sentence is not in itself a finding about the gene and the disease. The quoted sentences say what the papers report.
insomnia (2 papers, 2021 to 2022). A sleep disorder characterized by difficulty in falling asleep and/or remaining asleep. "Cognitive dysfunction was found to be mainly associated with anti-olfactomedin 1 (OLFM1) antibodies, and sleep dysfunction (insomnia) in patients was associated with anti-Gamma-crystallin N (CRYGN) antibodies." (PMID 35711412, 2022). "Furthermore, six autoantibodies were associated with specific psychopathology symptoms: anti-AP3B2 (persecutory delusions), anti-TDO2 (hallucinations), anti-CRYGN (initial insomnia); anti-APMAP (poor appetite), anti-OLFM1 (above-median cognitive function), and anti-WHAMMP3 (anhedonia and dysphoria)." (PMID 34518517, 2021).
CRYGN also shares sentences with these, for which no sentence is quoted: Delusion (1 paper); dysphoria (1); Hallucinations (1); leukemia (1); sleep dysfunction (1); thrombosis (1).